SLAMF8 (SLAM family member 8)
Description:
May play a role in B-lineage commitment and/or modulation of signaling through the B-cell receptor.
Synonyms: CD353; BLAME; SBBI42
Tractability: Antibody: UniProt predicts a signal peptide or a membrane-spanning region.
Gene: Protein-coding gene on chromosome 1 (159,826,693 to 159,837,492, forward strand). Ensembl gene ENSG00000158714.
Subcellular location: Membrane
Gene Ontology:
Molecular function: protein binding; identical protein binding; signaling receptor activity
Biological process: B-1 B cell lineage commitment; defense response to bacterium; immune response; leukocyte chemotaxis involved in inflammatory response; negative regulation of dendritic cell chemotaxis; negative regulation of macrophage chemotaxis; negative regulation of monocyte chemotaxis; negative regulation of neutrophil migration; negative regulation of respiratory burst involved in inflammatory response; phagosome acidification; regulation of B cell differentiation
Cellular component: cell surface; membrane
Genetic constraint (gnomAD): Loss-of-function variants: 24 observed, 31.6 expected, observed/expected ratio (o/e) 0.76, 90% interval 0.55 to 1.07. The upper end of that interval is the gene's LOEUF score, 1.07, which puts it in group 4 of 6, group 1 being the genes least tolerant of losing a copy. Missense variants: 381 observed, 373.1 expected, observed/expected ratio (o/e) 1.02, 90% interval 0.94 to 1.11. Synonymous variants: 139 observed, 152.91 expected, observed/expected ratio (o/e) 0.91, 90% interval 0.79 to 1.05.
Homologues: Orthologues: chimpanzee SLAMF8 (99% identical), macaque SLAMF8 (96% identical), pig SLAMF8 (79% identical), guinea pig SLAMF8 (78% identical), rabbit SLAMF8 (76% identical), mouse Slamf8 (75% identical), rat Slamf8 (71% identical), dog SLAMF8 (70% identical), tropical clawed frog slamf8 (35% identical), zebrafish si:cabz01074946.1 (14% identical). Paralogues in human: SLAMF9 (21% identical), SLAMF7 (21% identical), CD244 (20% identical), CD84 (19% identical), SLAMF1 (19% identical), LY9 (18% identical), CD48 (17% identical), SLAMF6 (15% identical), CD2 (14% identical).
Diseases named in the same sentence as SLAMF8 in open-access papers:
SLAMF8 is named in the same sentence as 41 diseases in open-access papers, as found by Europe PMC text mining. Sharing a sentence is not in itself a finding about the gene and the disease. The quoted sentences say what the papers report.
glioma (7 papers, 2019 to 2025). A benign or malignant brain and spinal cord tumor that arises from glial cells (astrocytes, oligodendrocytes, ependymal cells). "SLAMF8 expression in tumors was associated with worse outcomes in breast cancer and glioma, while serum expression in gastric cancer was associated with a good response to immunotherapy." (PMID 38476238, 2024). "In an assessment of TCGA glioma and the Chinese Glioma Genomic Atlas (CGGA) data, overexpression of SLAMF8 was associated with progression, higher grade glioma, and it was a biomarker for the mesenchymal subtype." (PMID 38476238, 2024). "In glioma, SLAMF8 may contribute to malignant progression, poor prognosis, and chemotherapy resistance through Toll-like receptors." (PMID 41162970, 2025). "Accordingly, high levels of CCR1 in patients with multiple myeloma have been linked to decreased overall survival, and increased levels of SLAMF8 mRNA have been identified as a prognosticator of worse survival in patients with high-grade gliomas and colorectal cancer." (PMID 37509358, 2023). "Additionally, higher SLAMF8 represented activation of antigen presentation and interferon-γ-mediated signaling in glioma." (PMID 35884843, 2022). "High expression of SLAMF8 was reportedly correlated with an enhanced T‐cell‐mediated immune phenotype and activated IFN‐γ signalling pathway in glioma." (PMID 34729183, 2021).
autoimmune disease (5 papers, 2015 to 2024). A disorder resulting from loss of function or tissue destruction of an organ or multiple organs, arising from humoral or cellular immune responses of the individual to their own tissue constituents. "Up-regulated SLAMF8 is associated with increased disease activity and inflammation in autoimmune diseases, and its involvement in the activation of macrophages during inflammation has been observed in cancer studies." (PMID 38542346, 2024). "Finally, we examined cis-pQTLs of the HLA-pGenes identified from the flagship pQTL study, and found that the cis-pQTLs of five HLA-pGenes—CD5, CD6, IL7R, SLAMF8, and TNFSF11—are themselves associated with autoimmune diseases with HLA risk." (PMID 39085222, 2024). "However, this CpG site is also an eQTM for five other genes in CD4+ T cells (TAGLN2, SLAMF8, DUSP23, PHYIN1 FCRL6), several of which have established autoimmune disease connections." (PMID 34946847, 2021).
gastric cancer (3 papers, 2019 to 2024). A primary or metastatic malignant neoplasm involving the stomach. "The analysis of survival indicated a connection between SLAMF8 and the overall prognosis in different types of cancers, where higher levels of SLAMF8 were found to be significantly linked to unfavorable outcomes in patients but favorable outcome of immunotherapy in gastric cancer." (PMID 38787377, 2024). "As a result, SLAMF8 may become an important prognostic biomarker in the majority of tumors and a hopeful gene target for immunotherapy against gastric cancer." (PMID 38787377, 2024). "High levels of SLAMF8 have been detected in the serum of patients with gastric cancer." (PMID 38476238, 2024). "Therefore, SLAMF8 is correlated with immune ‘hot’ gastric cancers that respond better to immune checkpoint blockade." (PMID 38476238, 2024). "In this study, we discovered that SLAMF8 was elevated in serum of gastric cancer patients." (PMID 30873760, 2019). "Furthermore, investigations in a gastric cancer model with Epstein-Barr virus (EBV) infection, which has been associated with improved responses to anti-PD-1 therapy, high SLAMF8 expression was found to be a factor that might be involved in these responses." (PMID 38476238, 2024).
colorectal cancer (2 papers, 2023). A primary or metastatic malignant neoplasm that affects the colon or rectum. "Further research has indicated a correlation between SLAMF8 expression and the presence of CD8-positive T cells in colorectal cancer." (PMID 37835502, 2023). "As delineated in the preceding sections, members of the SLAM family, notably SLAMF8 and SLAMF9, play a dynamic role in tumor-immune modulation, profoundly affecting the progression and therapeutic outcomes of malignancies like colorectal cancer and melanoma." (PMID 37835502, 2023). "This review delves into the roles of specific SLAM members, such as SLAMF8 and SLAMF9, and their impact on tumor progression in cancers like colorectal cancer and melanoma." (PMID 37835502, 2023).
liver inflammation (2 papers, 2022 to 2025). "Limited studies have indicated that combined deficiency of SLAMF8 and SLAMF9 prevents endotoxin-induced liver inflammation by downregulating TLR4 expression on macrophages, and SLAMF8 can negatively regulate ROS production by macrophages." (PMID 35432371, 2022). "The combined activation of SLAMF9 and SLAMF8 induces macrophage activity, while their downregulation modulates the expression of TLR4, thereby attenuating endotoxin-induced liver inflammation." (PMID 40473938, 2025).
melanoma (2 papers, 2022 to 2023). A malignant, usually aggressive tumor composed of atypical, neoplastic melanocytes. "The expression of SLAMF8 and PSMB8 could predict the efficacy of immune checkpoint inhibitor immunotherapy in gastrointestinal cancer and melanoma." (PMID 36225561, 2022).
neuroblastoma (2 papers, 2020 to 2022). Neuroblastoma (NB) is the most common solid, extracranial childhood tumor. "Nonetheless, our preliminary analysis indicates that other SLAM family genes are expressed at compatible levels to that of SLAMF7 in high-risk neuroblastoma tissues (SLAMF2, SLAMF5, and SLAMF8)." (PMID 35525858, 2022).
ovarian carcinoma (2 papers, 2019 to 2023). A malignant neoplasm originating from the surface ovarian epithelium. "Accordingly, the other four genes, namely FCGR2B, CD53, CCR1, and SLAMF8, were previously identified as integral components of a larger tumor associated macrophage-related signature with prognostic potential in patients with ovarian cancer." (PMID 37509358, 2023).
Salmonella Infections (2 papers, 2022 to 2025). Infections with bacteria of the genus SALMONELLA. "Since IFNγ increases SLAMF8 expression, and activation of pMø through IFNγ is crucial for Salmonella infection, we decided to analyze the impact of SLAMF8 in Salmonella-infected Mø." (PMID 35837407, 2022). "To analyze the role of SLAMF7 and SLAMF8 in human primary pDCs, we next examined the effect of the direct engagement of one of these two receptors by a specific antibody or its isotype control on the response of these cells to Salmonella infection." (PMID 40231463, 2025). "Indeed, prokaryotic RNA purified from E. coli or S. Typhimurium increased the percentage of SLAMF7+ and SLAMF8+ CAL-1 cells in an RNase-dependent manner, as well as the surface levels of SLAMF7 and SLAMF8, in primary human pDCs, like in the case of Salmonella infection." (PMID 40231463, 2025). "SLAMF7 and SLAMF8 signal through NF-κB, IRF7, and STAT-1, and limit mitochondrial ROS accumulation upon Salmonella infection." (PMID 40231463, 2025). "Enhanced iNOS activation, NO production, and IL-6 expression were also observed in the absence of SLAMF8 upon Salmonella infection, either in vivo or in vitro, while overexpression of SLAMF8 in RAW264.7 macrophages showed the opposite phenotype." (PMID 35837407, 2022). "Finally, we examined whether the higher levels of mtROS found in the absence of SLAMF7 or SLAMF8 influence the intracellular signaling initiated in pDCs by Salmonella infection." (PMID 40231463, 2025).
Alzheimer disease (1 paper, 2025). A progressive, neurodegenerative disease characterized by loss of function and death of nerve cells in several areas of the brain leading to loss of cognitive function such as memory and language. "In this study, analysis of the GSE122063 dataset from the Gene Expression Omnibus (GEO) database revealed that SLAMF8 is highly associated with Alzheimer’s disease (AD) and significantly upregulated in AD samples." (PMID 40394132, 2025). "This study aimed to investigate the expression and role of Signaling Lymphocytic Activation Molecule Family Member 8 (SLAMF8) in Alzheimer’s disease (AD), particularly its interaction with NINJ2 in the TLR4/NF-κB signaling pathway." (PMID 40394132, 2025). "Next, we investigated the molecular mechanisms through which SLAMF8 contributes to Alzheimer’s disease (AD) pathology." (PMID 40394132, 2025). "This study confirmed the elevated expression of SLAMF8 in Alzheimer’s disease (AD) by the analysis of data from the Gene Expression Omnibus (GEO) database." (PMID 40394132, 2025). "Additionally, we conducted a comprehensive evaluation of the expression levels of SLAMF8 in both Alzheimer’s disease (AD) cell and animal models." (PMID 40394132, 2025). "To gain deeper insights into the regulatory mechanisms of SLAMF8 in Alzheimer’s disease (AD), we assessed the expression levels of Toll-like receptor 4 (TLR4), phosphorylated p65 (phospho-p65), total p65, phosphorylated IκBα (phospho-IκBα), and total IκBα across different experimental groups." (PMID 40394132, 2025). "In conclusion, our study demonstrates that SLAMF8 and NINJ2 are key drivers of neuroinflammation and oxidative stress in Alzheimer’s disease by activating the TLR4/NF-κB pathway." (PMID 40394132, 2025).
anaplastic large cell lymphoma (1 paper, 2020). Anaplastic large cell lymphoma (ALCL) is a rare and aggressive peripheral T-cell non-Hodgkin lymphoma, belonging to the group of CD30-positive lymphoproliferative disorders, which affects lymph nodes and extranodal sites. "In this study, we found that some anaplastic large cell lymphoma (ALCL) samples were immunohistochemically positive for SLAMF8." (PMID 32054954, 2020).
Arthritis (1 paper, 2023). Inflammation of a joint. "Researchers have also found the knockout of SLAMF8 gene can alleviate arthritis in mice." (PMID 37277710, 2023).
Autoimmunity (1 paper, 2025). The occurrence of an immune reaction against the organism's own cells or tissues. "Given the consequences of elevated type I IFN secretion in various disorders, the involvement of SLAMF7 and SLAMF8 extends beyond infectious diseases to cancer and autoimmunity." (PMID 40231463, 2025).
benign prostatic hyperplasia (1 paper, 2025). A non-cancerous nodular enlargement of the prostate gland. "To assess SLAMF8 levels in PCa and examine its association with immune cell infiltration, we employed immunohistochemistry to measure the levels of SLAMF8, PD1, CD3, and CD19 in both PCa and benign prostatic hyperplasia (BPH) samples." (PMID 41162970, 2025).
breast carcinoma (1 paper, 2024). "In addition, one study found a correlation between a high expression of SLAMF8/CD353, tumor necrosis factor (TNF), and lymphocyte infiltration with a poor response to therapy in postmenopausal estrogen receptor (ER)+ breast cancer." (PMID 38476238, 2024).
brucellosis (1 paper, 2025). Brucellosis is a bacterial infection that spreads from animals to people via unpasteurized dairy products or by exposure to contaminated animal products or infected animals. "Altogether these data identify SLAMF7 and SLAMF8 as hallmarks of acute brucellosis and link their overexpression to type I IFN responses." (PMID 40231463, 2025). "Here, human blood transcriptomic analyses reveal the involvement of SLAMF7 and SLAMF8 in many infectious diseases, with elevated levels associated with type I IFN responses in salmonellosis and brucellosis patients." (PMID 40231463, 2025). "To determine whether SLAMF7 and SLAMF8 expression may vary in human pDCs during brucellosis, we infected CAL-1 cells with B. abortus or B. melitensis, the 2 main pathogenic species causing infection in humans." (PMID 40231463, 2025). "Here, we reveal the participation of SLAMF7 (CS1, CRACC, CD319) and SLAMF8 (BLAME, CD353) in a broad spectrum of infectious diseases, showing increased levels in the blood of salmonellosis and brucellosis patients that correlate with a type I IFN response." (PMID 40231463, 2025). "Several genes of the SLAM family (SLAMF1, SLAMF7, and SLAMF8) were overexpressed in acute but not in chronic brucellosis patients, unlike stable TLR9 gene expression." (PMID 40231463, 2025).
diarrheal disease (1 paper, 2025). The condition of having at least three loose or liquid bowel movements each day. "A second cohort of patients, comprising children under 10 years of age afflicted with diarrheal diseases, confirmed a significant upregulation of SLAMF7 and SLAMF8 in those diagnosed with Salmonella gastroenteritis." (PMID 40231463, 2025).
hepatocellular carcinoma (1 paper, 2024). A malignant tumor that arises from hepatocytes. "Immunohistochemistry was ultimately employed to validate the presence of the SLAMF8 gene in various tumor types including hepatocellular carcinoma, prostate adenocarcinoma, and kidney renal clear cell carcinoma." (PMID 38787377, 2024).
inflammatory bowel disease (1 paper, 2023). A spectrum of small and large bowel inflammatory diseases of unknown etiology. "The SLAMF8 gene is well known for its association with inflammatory bowel disease as indicated by human GWAS." (PMID 37277710, 2023).
metastatic prostate carcinoma (1 paper, 2025). A carcinoma that arises from the prostate gland and has spread to other anatomic sites. "SLAMF8 levels are useful for metastatic prostate cancer (AUC = 0.731)." (PMID 41162970, 2025).
peritonitis (1 paper, 2015). Inflammation of the peritoneum (tissue that lines the abdominal wall and covers most of the organs in the abdomen). "Three distinct in vivo models, i. e. skin sensitization by painting with the hapten FITC, thioglycollate induced peritonitis and migration in the lamina propria of the small intestine, were employed to demonstrate that migration of Slamf8-deficient DCs, macrophages and neutrophils is increased." (PMID 25799045, 2015). "We conclude that Slamf8-/- macrophages display a stronger migration response to the induction of peritonitis." (PMID 25799045, 2015).
prostate carcinoma (1 paper, 2025). A carcinoma that arises from epithelial cells of the prostate gland. "In this study, the overexpression of SLAMF8 in prostate cancer cells caused an increase in TLR4 expression, triggered the NF-κB signaling pathway, and led to higher IL-6 secretion, potentially contributing to an immunosuppressive tumor microenvironment." (PMID 41162970, 2025). "Finally, through cell and animal experiments, we further corroborated the association of SLAMF8 with prostate cancer progression and metastasis." (PMID 41162970, 2025). "Low expression of SLAMF8 was found to be significantly connected to a favorable prognosis in prostate cancer patients, as shown by the Cox regression model." (PMID 41162970, 2025). "We assessed SLAMF8’s prognostic value in prostate cancer across TCGA (n = 495), GSE11691 (n = 248), and MSKCC (n = 140) cohorts." (PMID 41162970, 2025). "SLAMF8 overexpression in prostate cancer cells promoted cell growth, lowered apoptosis rates, and boosted invasion in vitro, alongside hastening tumor development in mice." (PMID 41162970, 2025). "While our data nominates SLAMF8 as a compelling contributor to prostate cancer metastasis, its journey to clinical application requires rigorous validation." (PMID 41162970, 2025). "According to our previous study, SLAMF8 is an important marker for prostate cancer metastasis." (PMID 41162970, 2025). "The target gene, SLAMF8, emerges as a promising candidate for drug targeting and holds substantial potential for informing personalized and precise therapeutic strategies for prostate cancer patients." (PMID 41162970, 2025). "SLAMF8-positive prostate cancer patients may benefit from immunotherapy with MG-132-related drugs, but further studies are necessary to validate this conclusion." (PMID 41162970, 2025). "While this is a common limitation in large public genomic cohorts, our findings are presented in the context of prostate cancer broadly, and future studies with more detailed pathological annotations may help refine the prognostic and mechanistic role of SLAMF8 across specific subtypes." (PMID 41162970, 2025). "Consequently, SLAMF8 functions as a prognostic predictor for those with prostate cancer." (PMID 41162970, 2025). "According to the findings, SLAMF8 could potentially predict the immune status of prostate cancer." (PMID 41162970, 2025).
prostate tumor (1 paper, 2023). "Finally, both protein and RNA levels of SLAMF8 showed significant increases in prostate tumor tissues." (PMID 38017548, 2023).
viral infection (1 paper, 2019). "Insight into what role SLAMF8 could potentially be playing in myeloid cells of the CNS during viral infection comes from a report utilizing SLAMF8 knockout mice." (PMID 31744090, 2019). "Our current knowledge of SLAMF8 suggests it is sensitive to innate immune stimuli and has an immuno-regulatory role in macrophages; factors that suggest it may also be involved in immune regulation during viral infection." (PMID 31744090, 2019).